AFP (alpha fetoprotein)
Diseases named in the same sentence as AFP in open-access papers (continued):
Sharing a sentence is not in itself a finding about the gene and the disease.
liver fibrosis (continued). "The levels of ALT, AST, alpha-fetoprotein and serum creatinine were significantly higher in group with advanced liver fibrosis while serum albumin and prothrombin were significantly lower in the same group as compared to those with minimal fibrosis." (PMID 27785271, 2014). "Median values of AFP at liver fibrosis stages S0-1, S2, S3, and S4 were 3.0, 3.4, 5.4, and 11.3 ng/ml, respectively, and median APRI (AST/PLT ratio) was 0.41." (PMID 25128299, 2014). "Patients with elevated AFP showed higher serum ALT, lower platelet count and further progression of liver fibrosis compared to those with normal AFP." (PMID 22681639, 2012). "The age of the patients, serum AST level, platelets count and alpha fetoprotein combined together in predictive score of hepatic fibrosis as well as APRI, modified APRI and the FIB-4 were significant predictors of fibrosis." (PMID 23346149, 2012). "In our previous study among Egyptian patients, serum AFP remained independently associated with SVR after controlling for known factors associated with SVR, including liver fibrosis." (PMID 18545682, 2008). "In that study, it was the association between liver fibrosis and SVR which was completely removed after introducing serum AFP level into the model." (PMID 18545682, 2008). "One difference with our previous study is the disappearance of the association between AFP and SVR in multivariate analysis, after controlling for both serum GGT and liver fibrosis." (PMID 18545682, 2008). "This may be because the AFP levels correlate with the fibrosis stages, with higher levels of liver fibrosis often accompanied by elevated AFP levels." (PMID 40870838, 2025). "Furthermore, OPN shows promise as a clinical biomarker for detecting early-stage HCC and assessing liver fibrosis, potentially outperforming alpha-fetoprotein." (PMID 41388723, 2025). "A joint prediction model was constructed based on age, TNM stage, whether and how to operate, whether to receive radiotherapy, whether to receive chemotherapy, pre-treatment serum AFP status and liver fibrosis score." (PMID 37312022, 2023). "Thus, the combination of PLT and AFP enhanced the predictive performance of liver fibrosis in patients with CHB." (PMID 33289529, 2021). "For example, data regarding serum alpha-fetoprotein and liver fibrosis score, both demonstrating a good prognostic significance and commonly being considered in treatment decisions, were not captured by SEER until 2004 and were therefore excluded from this study." (PMID 34715816, 2021). "AFP and PLT levels were independently associated with LS, and their combined assessment could enhance the diagnostic and predictive performance of liver fibrosis among CHB patients." (PMID 33289529, 2021). "Univariate analysis showed that several factors were significantly associated with high IR, including indigenous race, high BMI (> 25 kg/m2), alcoholism, baseline elevated levels of ALT, alpha-fetoprotein, and triglyceride, as well as hepatic fibrosis (defined as FIB-4 > 3.25)." (PMID 35095765, 2021). "Hence, we recommend the use of AFP to predict liver fibrosis at the time of severe acute exacerbation of CHB, especially in the outpatients." (PMID 33289529, 2021). "Consistent with the regression analysis results, the presence of thrombocytopenia (PLT < 100 × 109/l) or high AFP levels (AFP > 8 ng/ml) improved the prediction of liver fibrosis, (OR = 6.763, 95% CI: 2.310–19.797, P<0.001 and OR = 18.804, 95% CI: 4.433–79.757, P<0.001), respectively." (PMID 33289529, 2021). "We analyzed the TBK1 expression based on eight widely recognized clinicopathological parameters of the HCC data set from TCGA, including age, gender, alpha-fetoprotein (AFP), tumor stage, tumor grade, T classification, vascular invasion, liver fibrosis, and the value of platelet-to-albumin ratio." (PMID 33679751, 2021).
liver fibrosis (continued). "In the present study, the main finding was that both AFP and PLT levels are independently associated with LS values and their combination could improve the prognostic prediction of liver fibrosis in CHB patients (AUC = 0.819)." (PMID 33289529, 2021). "In summary, the preoperative liver function indicators, the extent of liver fibrosis, and the AFP level differed significantly between the two groups before PS matching; however, 50 pairs were matched after PS matching, and all of their corresponding variables were balanced." (PMID 33319162, 2020). "CNALT patients displayed a higher platelet count (PLT) (170 000 vs 146 000/μL, P < 0.0001) and albumin (4.1 vs 4.1 g/dL, P = 0.0006) but lower AST (25 vs 51 U/L, P < 0.0001), alpha fetoprotein (3.2 vs 5.4 ng/mL, P < 0.0001), and liver fibrosis marker scores (all P < 0.0001)." (PMID 32782941, 2020). "This study demonstrated that whole-body insulin resistance and hepatic fibrosis correlated directly with elevated levels of AFP lifestyle modification over a 3-month period correlated with improved insulin resistance and a reduction in AFP levels." (PMID 27439433, 2016). "Interestingly recent studies pointed to correlation of liver fibrosis regression and low post treatment AFP levels after SVR." (PMID 27100663, 2016). "The association observed in this study between AFP, GGT, platelet count, and APRI may be attributable to the increased expression of hepatic progenitor cells (HPCs) in advanced hepatic fibrosis." (PMID 27335844, 2014). "Based on 12 available clinical parameters (age, sex, HBeAg status, HBV DNA, platelet, albumin, bilirubin, ALT, AST, ALP, GGT and AFP), a model to predict significant liver fibrosis (Ishak fibrosis score ≥3) was derived using the five best parameters (age, ALP, AST, AFP and platelet)." (PMID 21853071, 2011). "Higher levels of serum AFP may correspond to higher expression of HPC in individuals developing liver fibrosis." (PMID 18545682, 2008). "Thus, there seems to be important correlations among liver fibrosis, serum AFP, and serum GGT, one acting as a confounder of the other in the association with SVR depending on the study population." (PMID 18545682, 2008). "Notably, there was a moderate positive correlation between serum AFP levels and Scheuer’s classification (r = 0.511, p < 0.001), suggesting that serum AFP could be a potential biomarker for liver fibrosis." (PMID 37241155, 2023). "In addition, risk factors for hepatocarcinogenesis after an SVR in patients who receive IFN-based therapy include older age, advanced liver fibrosis, male sex, the AFP level after treatment, glucose metabolism disorders, lipid metabolism disorders and alcohol intake, and other factors." (PMID 35020772, 2022). "However, when we compared the impact of AFP combined with AST, and ALT on LS, the results showed that AFP level (AFP > 8 ng/ml) and high ALT/AST levels (ALT/AST > 2 ULN) predicted a significantly increased risk of liver fibrosis (OR = 11.968 for ALT and OR = 28.261 for AST)." (PMID 33289529, 2021). "However, in almost all reports, the background clinicopathological factors of patients with or without SVR were quite different; that is, patients in the SVR group were younger, had better liver function, less liver fibrosis, and lower levels of AFP at the time of the initial hepatectomy." (PMID 33319162, 2020). "Hence, the joint association observed in this study among AFP, GGT, liver fibrosis and SVR may be the reflection of more intense HPC expression in non responders compared to responders." (PMID 18545682, 2008). "Based on these reports, to predict the development of HCC in patients with chronic liver disease, we previously established a new scoring system, VFMAP, based on older age, male sex, liver fibrosis (VTQ), high AFP level, and fasting hyperglycemia." (PMID 38147196, 2024).
liver fibrosis (continued). "We suggested that patients with BMI ≤ 20.425, ECOG = 1–2, AFP ≥ 400 ng/ml, BCLC = C, HBV-positive and hepatic fibrosis required a lower dose of V15." (PMID 38376811, 2024). "Along with the idea that HCC develops on advanced liver fibrosis, the common brief among general clinicians is that HCC cases are usually accompanied by liver dysfunction, hepatitis viral infection, and positive AFP." (PMID 37998562, 2023). "Multivariate analysis suggested that age, pathological grade, AJCC stages, AFP, surgery, and tumor size were independent prognostic factors affecting the CSS of HCC patients with severe liver fibrosis, which were, therefore, included in the nomogram model." (PMID 35784933, 2022). "Eventually, 7 variables (age, pathological grade, AJCC stages, tumor size, AFP, surgery, and income) were selected to construct the nomogram to predict the probability of CSS in HCC patients with severe liver fibrosis." (PMID 35784933, 2022). "Most patients with advanced liver fibrosis had abnormal baseline levels of liver inflammation and fibrosis markers, including transaminases, FIB-4, AFP, and APRI." (PMID 34242330, 2021). "In our study the decreases in non-invasive serological markers (ALT, AFP) and VCTE fibrosis scores suggest a significant regression of inflammation and liver fibrosis in patients at SVR12 as compared to baseline." (PMID 34855920, 2021). "Our study indicated that serum AFP level was more reliable and effective than ALT or AST for the assessment of hepatic fibrosis progression in CHB patients." (PMID 33289529, 2021). "Several other variables have been proposed to contribute to liver fibrosis, such as platelet count, total protein, ALP, GGT, total billirubin, HA, CIV, and AFP in our study." (PMID 28486931, 2017). "In HCV infection, the risk factors for HCC development had been reported to include liver fibrosis stage, age, achieving SVR, and the serum AFP levels." (PMID 27002630, 2016). "CSS is noticeably shorter in AFP-positive patients than in AFP-negative patients, which reveals that AFP exhibits a substantial predictive value in predicting long-term CSS in HCC patients with severe liver fibrosis." (PMID 35784933, 2022). "This pattern was further supported by the statistically significant association between the expression levels of these genes with that of AFP (α-fetoprotein), TIMP1 (tissue inhibitor of metalloproteinase 1) and TGFB1 (transforming growth factor β1), which are known markers of liver fibrosis." (PMID 34440687, 2021). "Several combinations have been proposed, such as the SAFE biopsy algorithm for the non-invasive assessment of liver fibrosis, which consists of APRI and a commercialized method (Fibrotest-Fibrosure) or the combination of GP73, glypican-3, and AFP for the diagnosis of HCC." (PMID 34298722, 2021). "Alpha fetoprotein (AFP) and hepatic fibrosis score status could only be separated into a single stratified study for prognosis." (PMID 32110489, 2020). "AFP level (p=0.68) and the grade of liver fibrosis (p=0.37) were not statistically significant factors regarding achievement of CR." (PMID 30729099, 2019). "Compared with nonsignificant fibrosis patients (F0–1), patients with significant liver fibrosis (F2–4) had lower HBV DNA, HBsAg, HBeAg, and platelet count levels and higher anti-HBc, alpha-fetoprotein (AFP), AST, globulin, GGT, laminin, IV-C, LSM, and spleen thickness." (PMID 30405859, 2018). "The expression of COL1A1, AFP and ALB are correlated with progression of liver fibrosis." (PMID 30346985, 2018). "Secondary outcomes include changes in liver fibrosis using AST to platelet ratio index, changes in glucose and lipid levels, anthropometric measures, changes in alpha-fetoprotein levels, patient acceptability, and changes in dietary and physical activity parameters." (PMID 27439433, 2016).
liver fibrosis (continued). "The data obtained in these mice were compatible with a lack of effect of iRGD treatment on the blood AFP levels in the three mouse models of liver fibrosis, suggesting that iRGD may not affect AFP levels in mice with fibrotic livers in the absence of HCC." (PMID 38889481, 2024). "In fact, FIB-4 and AFP decreased and albumin and PT improved from baseline to EOT and SVR12; thus, achievement of SVR may have a strong impact on the development of HCC by improving liver fibrosis and inflammation." (PMID 37268672, 2023). "In addition, the LS value in high AFP level subgroups (AFP > 8 ng/ml) significantly improved the predictive ability of liver fibrosis compared with the low AFP level subgroups, which was not subjected to the ALT or AST values." (PMID 33289529, 2021). "However, recent studies postulated that AFP can be used in diagnosis and assessment of liver fibrosis without the presence of HCC." (PMID 27275221, 2015). "Patients with significant liver fibrosis (F2–4), in comparison with nonsignificant fibrosis (F0–1), had lower HBV DNA, HBsAg, HBeAg, and platelet count levels and higher anti-HBc, AFP, AST, globulin, GGT, laminin, IV-C, LSM, and spleen thickness." (PMID 30405859, 2018). "AFP may be used as an additional predictor of post-SVR LREs to enhance the performance of predictive models for liver-related pathogenesis, which may not be explained by liver fibrosis or its surrogate markers alone." (PMID 35837486, 2022).
teratoma (102 papers, 2003 to 2026). A non-seminomatous germ cell tumor characterized by the presence of various tissues which correspond to the different germinal layers (endoderm, mesoderm, and ectoderm). "After a surgical operation is performed the concentration of AFP in the blood serum of the newborn can be monitored to assess the risk of maliganacy and recurrence of a teratoma." (PMID 40041260, 2023). "With regard to the role of tumor markers in the diagnostic procedure, immature teratoma has been associated with elevated AFP serum levels, which have been reported in 33–65% of patients." (PMID 37508611, 2023). "Teratomas have been associated with elevated serum alpha fetoprotein levels along with intracranial anomalies including palatal fissures, hemicranias, anencephaly, and polyhydramnios." (PMID 23936713, 2013). "Teratomas are typically associated with normal serum tumor markers, although they may lead to a mild elevation in serum AFP levels." (PMID 38396829, 2024). "In this condition, growing benign mature teratoma masses are diagnosed during or after chemotherapy, despite normalization of serum levels of AFP, if previously elevated." (PMID 41118662, 2026). "Serum tumor markers normalized post-treatment in all but one patient with immature teratoma who had a reduced but persistently abnormal AFP." (PMID 40343905, 2025). "Elevated alpha-fetoprotein suggests the presence of other histological components in choriocarcinoma, such as embryos, teratomas, or yolk sacs." (PMID 40276055, 2025). "Based on the imaging findings and AFP results, we also considered teratoma in our differential diagnosis." (PMID 39421450, 2024). "Among patients with mature teratomas, the median AFP level of patients > 12 months old was within the normal range: while that of patients < 12 months old was 2.2 ng/ml." (PMID 36795187, 2023). "Among patients with immature teratomas, the median AFP level of patients > 12 months old is within the normal range: while that of patients < 12 months old was 82.2 ng/ml." (PMID 36795187, 2023). "Patients with mature teratomas were younger and had higher AFP levels and had larger testicular tumor diameters than did those with mature teratomas (P < 0.05)." (PMID 36795187, 2023). "In our clinical practice, normal AFP levels and teratomas diagnosed by ultrasonography can be used as two reference for the preoperative evaluation of benign testicular tumors." (PMID 36795187, 2023). "Regarding tumor markers, the mean value of AFP for immature teratomas (101.7 ng/mL, 3.8–185.2) was significantly higher than that of mature cystic teratomas (2.1 ng/mL, 0.6–5.7) (p < 0.01)." (PMID 37635241, 2023). "There are rare situations in which Wilms tumors consist of tissue resembling nephroblastoma as well as tissue morphologically corresponding to a teratoma, leading to AFP production." (PMID 37686577, 2023). "A remarkable finding is that although teratoma is normally characterized by normal STM, we found AFP elevation in 16 teratoma patients." (PMID 34518930, 2022). "Teratoma and schwannoma can be differentiated by tumor markers Alpha-fetoprotein (AFP) and CA-125, whereas schwannoma is suspected if these tumor markers are negative." (PMID 35749948, 2022). "The criteria favoring immature teratomas in prepubertal patients are the young age of the child, a larger tumor size and increased AFP level, with a cut-off of 8 months, 2.5 cm and 23 ng/mL, respectively." (PMID 35804952, 2022). "Neither histopathological diagnosis nor tumor markers alone reliably diagnose NGGCTs due to the secretion of HCG and AFP by germinomas and teratomas." (PMID 35205726, 2022). "The patient who had a normal serum AFP level and was diagnosed with immature teratoma on biopsy underwent primary tumor excision first." (PMID 33530223, 2021). "One (case No. 1) was diagnosed with malignant recurrence with a yolk sac component (AFP level 330,181 ng/mL) at 2.1 years of age from a neonatal sacrococcygeal mature teratoma." (PMID 33530223, 2021).